L1CAM (L1 cell adhesion molecule)
Diseases named in the same sentence as L1CAM in open-access papers (continued):
Sharing a sentence is not in itself a finding about the gene and the disease.
tumor (continued). "In this context is worth mentioning that high expression of L1CAM in OC is associated with the rapid growth of aggressive tumours and a poor prognosis for the patients." (PMID 30253737, 2018). "Among metastatic EC, the highest levels (60%) and the median level (24%) of L1CAM in tumors correlate with the progression, suggesting that the expression of this molecule is linked to the tumor component most involved in metastatic processes." (PMID 29980240, 2018). "CD171 (L1-CAM) is a cell surface adhesion molecule expressed at high levels on different solid human tumors that has been associated to tumor progression." (PMID 30510968, 2018). "Our study confirmed that L1CAM expression of the tumour is associated with poor differentiation and patients with L1CAM positive tumours were more likely to belong to groups of higher risk of relapse." (PMID 29980240, 2018). "L1CAM expression was strongly associated with percentage of vimentin expressing tumor cells (P = 0.003), and expression of both L1CAM and vimentin indicated a subgroup with the highest change of recurrence (HR 3.15, 95% CI 1.25 – 7.92, P = 0.015)." (PMID 29152102, 2017). "In conclusion, compelling evidence supports the aberrant expression of L1CAM in cancer-associated vasculature, where it plays a pleiotropic role that ultimately sustains tumor angiogenesis and counteracts vessel maturation." (PMID 28134764, 2017). "L1CAM plays multiple pro-angiogenic roles in the endothelial cells of tumor-associated vessels, thus emerging as a potential therapeutic target." (PMID 28134764, 2017). "Percentage of vimentin expressing tumor cells was strongly associated with L1CAM expression (P = 0.003, One-way ANOVA)." (PMID 29152102, 2017). "We investigated the association between L1CAM expression and survival, as well as the association between L1CAM expression and percentage of vimentin expressing tumor cells." (PMID 29152102, 2017). "L1CAM expression in Mint3 KO MEFs significantly increased the ratio of MEFs associated with phospho-ERK1/2-positive cells in the tumour." (PMID 28504692, 2017). "Positive L1CAM expression (≥10% of tumor cells) was associated with disease-free survival, validated using RNAseq TCGA data." (PMID 29152102, 2017). "As L1CAM expression has been related to EMT, we assessed the association between L1CAM expression and the percentage of vimentin expressing (keratin positive) tumor cells, determined by flow cytometry." (PMID 29152102, 2017). "The functional implications of de novo expression of L1CAM in cancer-associated vessels are not limited to the tumor-endothelial crosstalk." (PMID 28134764, 2017). "As L1CAM is thought to play a role in EMT, we investigated the association between L1CAM expression and percentage of vimentin expressing tumor cells, assessed by flow cytometry." (PMID 29152102, 2017). "In our study, L1CAM-expression was associated with predictors of poor clinical outcome like tumor grade and LVSI." (PMID 26891628, 2016). "Our study confirmed that L1CAM expression of the tumor is associated with poor differentiation and patients with L1CAM positive tumors were more likely to belong to groups of higher risk of relapse." (PMID 27488577, 2016). "They found that blockage of L1CAM led to an increase in apoptosis and a decrease in tumor vascularization, caused by a down regulation of VEGF expression." (PMID 27174921, 2016). "High L1CAM expression was associated with high tumor grade (p=0.04) and L1CAM mRNA levels increased with tumor stage (p=0.025)." (PMID 27174921, 2016).
tumor (continued). "L1-CAM has also been implicated in promoting tumor cell proliferation, as well as migration, invasion and metastasis." (PMID 26761817, 2016). "L1CAM-expression was associated with advanced age, poor tumor grade, and lymphovascular space invasion." (PMID 26891628, 2016). "Several studies have shown that L1CAM-expression is associated with aggressive carcinoma subtypes and tumor progression." (PMID 26891628, 2016). "EMT has been associated with an increased invasiveness of tumor cells, and previously published reports showed that L1CAM triggers cell migration and invasion in several tumor types." (PMID 25860483, 2015). "Both cancerous and endometriotic tissues were positive for L1CAM-antibodies, which are associated with a high risk of tumor relapse and short survival rates." (PMID 24371719, 2013). "The CAR was targeted against tumour-associated CD171 (L1 cell adhesion molecule) and contained a CD3ζ endodomain." (PMID 23304553, 2012). "As the results, we found that the high expression of L1CAM was significantly associated with advanced tumor stage (P = 0.02) and advanced tumor grade (P = 0.03), respectively." (PMID 22888955, 2012). "In the case of the L1 cell adhesion molecule (L1CAM), which is expressed in many human tumours and often linked to bad prognosis, alternative splicing results in a full-length form (FL-L1CAM) and a splice variant lacking exons 2 and 27 (SV-L1CAM)." (PMID 21541352, 2011). "With regard to tumour pathology, overexpression of L1CAM is detected in a variety of cancers and associated with tumour growth and metastasis." (PMID 21541352, 2011). "Wherever investigated, the expression of L1CAM was associated with bad prognosis suggesting that, directly or indirectly, L1CAM drives tumour progression." (PMID 20799950, 2010). "Moreover, L1CAM was found to be expressed in cancer tissues and cell lines, which are associated with aggressive tumor characteristics and lower overall survival rates." (PMID 40699746, 2025). "L1CAM is a transmembrane glycoprotein implicated in tumour growth and metastasis." (PMID 41561510, 2025). "Our study, like previous reports, did not include Birt–Hogg–Dubé-associated tumors, such as hybrid oncocytic/chromophobe neoplasms, which may occasionally express L1CAM." (PMID 40805143, 2025). "Given their shared characteristics in tumor progression, it is plausible that L1CAM may be associated with FOXC1 in TNBC." (PMID 38183514, 2024). "On the other hand, CD133 expression was significantly associated with CD44 expression (p = 0.004, OR: 9.778, 95% CI: 1.762–54.263), L1CAM expression (p = 0.024, OR: 4.714, 95% CI: 1.178–18.861) and marginally associated with moderately differentiated tumor histology." (PMID 39148690, 2024). "To examine whether L1CAM contributes to phenotypes associated with tumor dissemination and metastasis, we used RNA interference to evaluate the impact of L1CAM knockdown on the migration of OVCAR8, CAOV3 and FT282CE cells." (PMID 36509990, 2022). "Furthermore, L1CAM overexpression in these cancer contexts is generally associated with poor prognosis, an invasive phenotype, advanced tumor stages, and chemotherapy resistance." (PMID 36387224, 2022). "Additionally, the percentage of CD4+FOXP3+ Tregs in tumor tissues exhibited a significant positive association with L1CAM and CCL22 in patients with ESCC." (PMID 33710805, 2021). "For this, we have performed a systematic review on current literature, in which we have specifically screened for publications in which L1CAM functions were linked to information on relevant protein domain and on linked downstream signaling pathways in tumor cells." (PMID 31455004, 2019).
tumor (continued). "Shedding of L1CAM-ECD appears a common tumor-progression-associated mechanism." (PMID 31455004, 2019). "Furthermore, our earlier reports demonstrated that L1CAM is expressed in tumor-associated vasculature." (PMID 30829570, 2019). "High L1CAM expression is associated with advanced tumor stages, metastases and poor prognoses." (PMID 31455004, 2019). "Both cell types cultured in higher concentration of glucose (4.5 g/L) expressed lower levels of L1CAM compared to cells cultured in 1 g/L glucose, indicating that the expression of L1CAM might be linked to glycolytic energy metabolism of tumor cells." (PMID 29615539, 2018). "If their finding is reproduced in other studies, it may further expand the potential of L1CAM IHC to refine the prognosis of intermediate-risk tumours." (PMID 30050154, 2018). "L1CAM expression was independently associated with locoregional recurrence-free survival (hazard ratio 2.62, 95% CI 1.33 – 5.17, P = 0.006), and strongly associated with percentage of vimentin expressing tumor cells (P = 0.003)." (PMID 29152102, 2017). "Furthermore, we determined the association between L1CAM expression and percentage of vimentin expressing tumor cells, as a marker for EMT." (PMID 29152102, 2017). "Additionally, EMT and NF-κB activation is associated with the up-regulation of L1CAM, which enhances cell invasion and motility and tumor metastasis formation." (PMID 27285767, 2016). "Likewise to FoxP3, tumor cell associated expression of L1CAM has been shown to confer immunosuppressive functions to CD4+ T cells in vitro (unpublished observations)." (PMID 24797069, 2014). "Furthermore, L1CAM has been associated with metastasis and angiogenesis during tumor progression by promoting cancer cell adhesion to endothelial cell monolayers, and via transendothelial migration." (PMID 24660028, 2014). "Additionally, the high expression of L1CAM was significantly associated with advanced tumor stage (P = 0.02) and advanced tumor grade (P = 0.03), respectively." (PMID 22888955, 2012). "As elevated invasive potential is one driving force of metastasis and L1CAM has been shown to promote cell invasion, we investigated whether FL-L1CAM caused an increase in the invasive potential of tumour cells." (PMID 21541352, 2011). "In summary, the clinical utility of L1CAM as a diagnostic and prognostic factor has emerged from many studies in different types of cancers, albeit with some controversial observations, which is in line with its involvement in malignancy-associated features of tumor cells." (PMID 32429448, 2020). "Indeed, L1CAM has emerged as a causal factor in tumor invasion and metastasis." (PMID 32429448, 2020). "Furthermore, L1CAM expression was strongly associated with percentage of vimentin expressing tumor cells and expression of both L1CAM and vimentin indicated a subgroup with the highest change of recurrence, suggesting that L1CAM ascertains tumor aggressiveness, possibly through EMT." (PMID 29152102, 2017). "In the present study we wished to clarify i) whether L1CAM expression in ECs involves epigenetic mechanisms in cell lines and primary tumor tissues and ii) whether L1CAM and the CT-X genes, all encoded in the same locus on the X-chromosome, bear some similarity in their epigenetic regulation." (PMID 23530769, 2013). "Furthermore, possibly due to SV-L1CAM being seemingly tumour-associated, nobody had so far challenged the hypothesis that SV-L1CAM is also functionally the most important L1CAM variant for tumour progression." (PMID 21541352, 2011). "Tumor-infiltrating L1CAM-CAR T cells expressed lower levels of the selectin P ligand (SELPLG) glycoprotein and higher levels of the T cell-specific adaptor protein, SH2D2A." (PMID 41394860, 2025). "Membranous L1CAM staining was found in 1,175 (9.1%) of 12,888 interpretable tumor samples, including 301 (2.3%) with weak, 569 (4.4%) with moderate, and 305 (2.4%) with strong positivity." (PMID 41328908, 2025).
tumor (continued). "A predominantly membranous L1CAM staining was found in 1,175 (9.1%) of the 12,888 interpretable tumor samples, including 301 (2.3%) with weak, 569 (4.4%) with moderate, and 305 (2.4%) with strong positivity." (PMID 41328908, 2025). "L1CAM is a neural cell adhesion molecule that has been increasingly recognized for its role in tumor progression, particularly in enhancing cancer cell motility, invasion, and perineural invasion." (PMID 40963905, 2025). "L1CAM promotes tumor growth, invasion, and immune suppression, which leads to the formation of new metastases and perineural invasion." (PMID 40699746, 2025). "Here we implemented an in vitro strategy to identify genes driving L1CAM-CAR T cell migration into a 3D tumor mass." (PMID 41394860, 2025). "Our current study advances the understanding of PDAC pathophysiology by elucidating the role of L1CAM in the dynamics of collagen deposition within the tumor microenvironment." (PMID 40770187, 2025). "Instead, we propose that specific tumor epithelial subsets, particularly those with low L1CAM expression (L1low), can actively influence collagen dynamics." (PMID 40770187, 2025). "Interrogating the single-cell RNA sequencing (scRNA-seq) Atlas database, which includes 10 functionally distinct clusters of both tumor and normal samples, we observed mutually exclusive expressions patterns of L1CAM and COL17A1." (PMID 40770187, 2025). "The potential role of L1CAM in tumor progression, in combination with its membranous location and its expression in only a few normal cell types, makes L1CAM an attractive candidate drug target." (PMID 41328908, 2025). "The downregulated proteins in both tumor types were predominantly involved in synaptic signal transmission and L1CAM interaction." (PMID 39716938, 2025). "On day 14, the median luminescent signal of SELPLG-deficient L1CAM-CAR T cells was significantly stronger in the tumor compared to L1CAM-CAR T cells retaining endogenous SELPLG expression." (PMID 41394860, 2025). "T cell homing to the tumor site was comparable between the two L1CAM-CAR T cell populations until day 14 after adoptive transfer." (PMID 41394860, 2025). "L1CAM-knockout tumours rapidly grew by day 11 (median survival: 7 days), while partial remission occurred in three animals bearing unmodified tumours, (assessed until day 22, median survival: 11 days)." (PMID 41366257, 2025). "L1CAM facilitates tumor growth by facilitating cell multiplication, invasion, and resistance to chemotherapy while also affecting the dynamics of the tumor environment." (PMID 40699746, 2025). "IVIS imaging demonstrated that circNFIB overexpression promoted tumor spread along the sciatic nerve, while this effect was markedly attenuated by L1CAM silencing." (PMID 40963905, 2025). "A recent study has revealed that CRC migration occurs along enteric neurons partly via L1CAM and N‐cadherin supporting long and fast invasion of tumour cells." (PMID 40374531, 2025). "In a study that analyzed 107 surgically resected PDAC specimens, it was found that L1CAM was positively expressed in 23 cases (21.5%), primarily at the tumor’s invasive surface." (PMID 40699746, 2025). "Its downregulation is linked to increased tumor aggressiveness, enhanced EMT, and metastatic potential via upregulation of ERBB2 and L1CAM expression." (PMID 40805172, 2025). "In OC patient-derived cancer stem cells (CSCs), L1CAM was found to promote stemness-related properties including sphere formation, tumor initiation, and chemoresistance." (PMID 40429728, 2025). "Our study investigates the role of collagen dynamics in PDAC, revealing that TGF-β1 negatively regulates the expression of L1 cell adhesion molecule (L1CAM), leading to a more invasive tumor phenotype." (PMID 40770187, 2025).
tumor (continued). "Many studies on cancer cell lines have demonstrated the role of full-length L1CAM in promoting tumor progression." (PMID 41301764, 2025). "L1CAM- CAR T cells capable of infiltrating the tumor model were separately analyzed using single-cell and bulk RNA sequencing, and compared to CAR T cells that did not enter the 3D tumor model." (PMID 41394860, 2025). "Concurrently, CD24 facilitates the immune evasion of tumor cells by recognizing Siglec‐G/10 on macrophages, P‐/E‐selectin on endothelial cells, and L1CAM on lymphocytes." (PMID 41354057, 2025). "Continuing this research, the authors showed that overexpression of L1CAM in ovarian cell lines enhanced the migration of tumor cells and resulted in better tumor growth in mice." (PMID 40870967, 2025). "Nearly twice as many CD28-costimulated L1CAM-CAR T cells infiltrated (mean=196,839 T cells, range=190,276-201,389 cells) the tumor model compared to 4-1BB costimulated L1CAM-CAR T cells (mean=104,381 T cells, range: 87,304-129,403)." (PMID 41394860, 2025). "We focused on the highly metastatic H-CTC subtype and its L1CAM expression pattern to explore its link with tumor aggressiveness." (PMID 41306535, 2025). "Exhibits variable prognosis; intermediate outcomes depending on tumour grade, stage, and L1CAM expression." (PMID 41312167, 2025). "A total of 74 of 135 tumor entities (54.8%) showed L1CAM staining in at least one case, and 36 tumor categories (26.7%) included at least one case with strong L1CAM staining." (PMID 41328908, 2025). "Additionally, the Ki-67 high-expression group showed a significantly greater number of L1CAM+ T-CTCs (5.02 ± 6.989) compared to the low-expression group (2.51 ± 4.726, p = 0.042), suggesting that L1CAM+ T-CTCs may be associated with tumor cell proliferative activity." (PMID 41306535, 2025). "Increased levels of L1CAM facilitated cell growth, movement, invasion, tumor development, and the spread of cancer, through the activation of the PI3K/Akt signaling pathway." (PMID 40699746, 2025). "Proteolytic cleavage and exosome formation resulted in soluble L1CAM forms that retained functional similarities to the full-length protein, but also introduced unique mechanisms, impacting tumor progression indirectly." (PMID 40699746, 2025). "L1CAM enhances cell proliferation and tumor growth by engaging integrin signaling and activating NF-κB." (PMID 40699746, 2025). "This led to cleavage of L1CAM, limiting tumor spread along vessels, and generation of soluble factor-related apoptosis ligands (sFasL), inducing tumor apoptosis." (PMID 40733107, 2025). "CAR T cell efficacy and tumour control in mice bearing L1CAM-high (SK-N-BE2c) tumours, however, varied across treatment groups." (PMID 41366257, 2025). "Glial fibrillary acidic protein (GFAP)+/S100β+ astrocytes secrete PA, which induces tumor cell apoptosis and limits the activation of L1CAM to restrict tumor dissemination." (PMID 41429896, 2025). "Tranilast treatment not only attenuated tumor volume and collagen deposition but also appeared to promote L1CAM expression." (PMID 40770187, 2025). "Regarding L1CAM, tumor samples of 865 patients were tested with the clone 14.10 (1:500 dilution), and a 10% tumor cell positivity was used as the cutoff value." (PMID 40870967, 2025). "Gross anatomical examination of the sciatic nerve region revealed restricted tumor extension in the L1CAM knockdown group." (PMID 40963905, 2025). "The biological role of extracellular sL1CAM has been less extensively studied compared to the full-length form of L1CAM, but there is evidence suggesting its role in promoting tumor progression." (PMID 41301764, 2025). "The 3D-tumor models were cocultured with CD28- or 4-1BB-costimulated L1CAM-CAR T or untransduced T cells." (PMID 41394860, 2025). "There were increased levels of FoxP3, vimentin, and L1CAM in PDAC cells, along with tumor-associated macrophage localization linked to tumor grades." (PMID 40699746, 2025).